IL4 (interleukin 4)
Diseases named in the same sentence as IL4 in open-access papers (continued):
Sharing a sentence is not in itself a finding about the gene and the disease.
psoriasis (continued). "Likely, the IL-4/STAT6 and IL-4/GATA3 signaling pathways prevent hyperactive Th1 responses in psoriasis." (PMID 37270497, 2023). "The anti-inflammatory genetic mediators associated with psoriasis are IL1RN, IL4, IL10, IL13, and IL19." (PMID 37569685, 2023). "For example, some studies found that IL-4 secreted by Th2 polarized T cells was increased in psoriasis patients, while other scholars indicated that this cytokine was decreased psoriasis patients." (PMID 36618400, 2022). "We found that the proportion of IL-4+ in CD4+ (Th2) cells was significantly higher in psoriasis patients than in HCs." (PMID 35927231, 2022). "Wikstroemia species ameliorated AD-like skin lesions and decreased serum IL-4 and IgE levels in mice, and the genus Daphnopsis has been used in diuretic, laxative, and psoriasis remedies." (PMID 36364783, 2022). "Cytokines such as IL-17A, IL-17E, IL-4 and IL-36γ regulate the inflammatory responses in keratinocytes in both AD and psoriasis." (PMID 36271146, 2022). "In our opinion, the reason why iNKT cells in psoriasis patients secreted higher levels of IL-4 and IL-17 mainly lies in the increase of iNKT2 and iNKT17 subsets." (PMID 35186952, 2021). "The promising outcome of IL-4 therapy in psoriasis implies an importance of evaluation of IL-4 treatment in other autoimmune diseases, such as RA." (PMID 34831223, 2021). "Polarized by Th2 cytokines (e.g., IL-4), M2 macrophages involved in anti-inflammation and repair process in psoriasis by secretion anti-inflammation cytokines (e.g., IL-10, Arg-1)." (PMID 33858431, 2021). "But we also found that iNKT cells in psoriasis patients secreted higher levels of IL-4 and IL-17, which is consistent with the increase observed in the sublineages of iNKT cells in psoriasis patients." (PMID 35186952, 2021). "Anti-inflammatory roles of IL-4 and IL-13 are well documented in the pathogenesis of psoriasis, type I diabetes, and experimental autoimmune encephalomyelitis (EAE)—the animal model of multiple sclerosis." (PMID 34831223, 2021). "The dysregulated expression of FLG, FLG2, LOR, and IVL is known to be normalized by specific biologic treatments, for example, blockade of interleukin-4 (IL-4) and IL-13 in AD or blockade of IL-17A in psoriasis." (PMID 32751111, 2020). "An excellent therapeutic response to biologics indicates a pivotal pathogenic role of interleukin (IL)-4/IL-13 signaling in AD and the tumor necrosis factor (TNF)-α/IL-23/IL-17A axis in psoriasis." (PMID 31683543, 2019). "A selective AHR agonist, tapinarof is currently being studied because this medicinal agent improves both psoriasis and AD in which different pathomechanisms operate (the TNF-α/IL-23/IL-17 axis in psoriasis and IL-4/IL-13 signaling in AD)." (PMID 31683543, 2019). "To validate the data obtained by microarray, we performed qRT-PCR and included AD like conditions (IL-4 and IL-13 treatment) as well as psoriasis like conditions (IL-22, OSM, IL-17, and TNFα treatment) in our experimental setup." (PMID 28928464, 2017). "The 3D skin equivalents were incubated, up on day four for the following three days under AD like conditions (IL-4 and IL-13), psoriasis like conditions (IL-22, OSM, IL-17, and TNFα) or left untreated." (PMID 28928464, 2017). "In psoriasis, T-cells (both CD4+ and CD8+) are known to cause low production of Th2 cytokines (IFNγ, TNFα, and IL-2) and high production of Th1 cytokines (IL-4, IL-6 and IL-10), leading to polarization of the type 1 pathway." (PMID 26849645, 2016). "For instance, IL-4 was decreased in human psoriasis patients and IL-4 therapy induced TH2 responses and improved their clinical states." (PMID 27095999, 2015). "We genotyped seven single-nucleotide polymorphisms (SNPs) in candidate genes of six ILs: IL4, IL10, IL12B, IL13, IL15, and IL23R, which have been shown in the literature to be associated with psoriasis in other ethnic groups." (PMID 24971308, 2014).
psoriasis (continued). "Treatment of psoriasis patients with subcutaneous injections of IL-4 polarizes lesional T cell responses to a Th2-type and decreases psoriasis severity." (PMID 23472158, 2013). "In these models, we finally analyzed the effects of the change from IL-17 (Th17, psoriasis) to IL-4/IL-13 (Th2, AD), in the same cytokine background (TNFα and IL-22)." (PMID 23193414, 2012). "At the time, the beneficial effect of IL-4 in psoriasis was attributed to theTh2-inducing and Th1 inhibitory capacity of IL-4 together with modulation of IL-23production by dermal inflammatory APC." (PMID 21611195, 2011). "Because there is an increase in circulating Type 1 T cells in psoriasis patients, we measured the effect of alefacept on circulating populations of Type 1 (IFN-γ-producing) and Type 2 (IL-4-producing) T cells by flow cytometry." (PMID 17555598, 2007). "Peripheral Type 1 deviation previously observed in psoriasis seems to be largely corrected through alefacept administration, as Type 1 T cells are significantly reduced at week 13, but Type 2 (IL-4 producing) T cells are comparatively unaffected." (PMID 17555598, 2007). "This case of lebrikizumab-induced psoriasis in a patient with AD supports the concept that inhibition of IL-13, like IL-4, may play a role in shifting the immune response toward the Th17 axis, precipitating psoriatic disease." (PMID 41542312, 2026). "Paradoxical psoriasis following treatment with IL-4/IL-13 inhibitors like dupilumab, but historically not with selective IL-13 inhibitors, has led to the hypothesis that IL-4 blockade is the key driver of this phenomenon." (PMID 41542312, 2026). "IL-4 exerts a suppressive effect on the Th17 pathway; therefore, IL-4 inhibition may shift immune responses toward Th17-mediated inflammation, a central pathway in psoriasis pathogenesis." (PMID 41542312, 2026). "Biologics used in psoriasis predominantly target TNFα, IL-17, 23, while in AD inhibit IL-4,13,31." (PMID 41481132, 2026). "The development of psoriasis involves numerous inflammation-related genes, including TNF (encoding tumor necrosis factor), CD4 (encoding the CD4 molecule), IL-10 (encoding Interleukin-10), and IL-4 (encoding Interleukin-4)." (PMID 40678620, 2025). "The proposed mechanism involves a shift in immune balance by suppressing the Th2 pathway via IL-4/IL-13 blockade; dupilumab may unmask latent Th1/Th17-driven conditions, such as psoriasis." (PMID 41281095, 2025). "IL-17 and IFN-γ, which play a critical role in the pathogenesis of psoriasis, significantly enhanced the R7-triggered IL-6 secretion, and the Th2 cytokines IL-4 and IL-13, which play a critical role in the pathogenesis of AD, tended to enhance the stimulatory effect of R7 on IL-6 secretion." (PMID 40461723, 2025). "Psoriasis was traditionally viewed as a Th1-mediated disorder, largely due to elevated IFN-γ production by CD4+ T cells within psoriatic lesions and minimal expression of Th2-associated cytokines such as IL-4, IL-5, and IL-13." (PMID 41226338, 2025). "In psoriasis, pruritus involves Substance P, IL-2, calcitonin gene-related peptide (CGRP), μ-opioid receptors (OPRM), and κ-opioid receptors (OPRK), while in AD pruritus is linked to thymic stromal lymphopoietin (TSLP), CGRP, IL-4, IL-13, and IL-31." (PMID 39859462, 2025). "While IFNγ and the IL‐17/IL‐23 axis are well established in psoriasis, IL‐4 has been shown to downregulate IL‐1β and IL‐6 production by psoriatic cells and may aid in psoriasis resolution, as observed during treatment with vitamin D3 analogues." (PMID 40926620, 2025). "Furthermore, new‐onset psoriasis can occur during anti‐IL‐4 receptor alpha treatment (dupilumab), suggesting a suppressive role mediated by the IL‐4/IL‐13 axis." (PMID 40926620, 2025). "The mechanisms of different biologics on IL-4 and IL-13 levels in individual patients with psoriasis remain unclear and need to be elucidated in the future." (PMID 38791078, 2024).
psoriasis (continued). "Th1 cells are the main source of pro-inflammatory cytokines such as TNF-α, IFN-γ, and IL-2 in the peripheral blood and lesion areas of psoriasis patients, while Th2 cells mainly secrete the cytokine IL-4, which significantly increases in patients with erythrodermic psoriasis." (PMID 38255845, 2024). "In addition, there is a decrease in the activity of CD4+ lymphocytes, and an increase in the production of IL-4, which has an anti-inflammatory effect in psoriasis." (PMID 36675592, 2023). "Cytokines related to type II immune response, such as IL-4, could suppress the IL-17/23 axis of psoriasis in lesional skin." (PMID 36865550, 2023). "IL-4, together with IL-10 that are secreted by Th2 cells as well, act as anti-inflammatory effectors to suppress Th1 differentiation and production of Th1-associated IFN-γ and TNF-β, thereby attenuate the inflammatory response in psoriasis." (PMID 37270497, 2023). "IL-4 promotes the differentiation of T-helper 2 and B cells for defense against parasites and is involved in the development of allergic and autoimmune diseases such as Hashimoto’s thyroiditis and psoriasis." (PMID 37513704, 2023). "A prospective dose-escalation study of human IL-4, which included 20 patients with severe psoriasis, revealed that IL-4 treatment markedly improved psoriasis and induced a pronounced skewing toward Th2 cytokine production in both psoriatic skin lesions and the circulation." (PMID 35884790, 2022). "In addition, etanercept reduced the levels of TNF‐α and IL‐6/12/23, and enhanced the levels of IL‐4/10, reduced Th17/Treg ratio and facilitated the polarization of macrophages to M2 in psoriasis model mice." (PMID 36444619, 2022). "The role of other cytokines in psoriasis is often controversial, including IL-4, IL-10, and IL-13." (PMID 36618400, 2022). "Therefore, we examined the possible correlation of key cytokines (IL-1β, TNF-α, IL-4, and IL-6) known to drive crosstalk between KCs and immune sentinels, which results in psoriasis development, with the induction of miR-21-5p or miR-21-3p expression." (PMID 34685526, 2021). "Moreover, miR-340 directly targets the pro-inflammatory cytokines IL-4 and IL-17A in psoriasis mice model, where Th17 cells and the consequent IL-17A production are implicated in the pathogenesis of this autoimmune disease as in others such as IBD." (PMID 34884564, 2021). "We didn’t found difference in the ratio of IL-17-producing iNKT cells vs IFN-γ-producing iNKT cells and the ratio of IL-4-producing iNKT cells vs IFN-γ-producing iNKT cells between psoriasis patients and healthy controls, which indicated there were no imbalance between them." (PMID 35186952, 2021). "The JAK/STAT signaling and spleen tyrosine kinase (SYK) pathways are implicated in numerous autoimmune and inflammatory diseases (e.g. AD, psoriasis, alopecia areata), modulating a range of immune responses, including the Th2 (IL-4, IL-13, CCL18), Th1 (IFNγ), and Th17/Th22 (CCL20, S100As) pathways." (PMID 33329590, 2020). "Results from a pooled analysis conducted by us also indicated that levels of interferon-γ, IL-17, IL-23, and tumor necrosis factor-α were significantly increased, whereas those of IL-4 and IL-10 were significantly decreased in the sera of patients with blood-heat syndrome of psoriasis." (PMID 32228720, 2020). "3D skin equivalents made of GATA3 shRNA transduced cells showed the tendency to express less FLG when compared to the respective control 3D skin equivalent under all investigated conditions (ns, AD-like (IL-4 and IL-13), and psoriasis-like (IL-22, OSM, IL-17, and TNFα) conditions)." (PMID 28928464, 2017). "It has been shown that serum levels of IFN-γ are much higher in patients with psoriasis than in controls and were correlated with the PASI score (psoriasis activity and severity index), whereas levels of Th2 cytokines (IL-4 and IL-10) were reported to be lower." (PMID 27274756, 2016).
psoriasis (continued). "In psoriasis an association with three variants of the IL-13 gene was observed: rs1800925, rs20541, and rs848 (This cytokine, such as IL-4 and IL-10, is secreted by Th2 lymphocytes and seems to be important in the innate and adaptive immune response dysregulation that leads to psoriasis)." (PMID 23971052, 2013). "Similarly, transdermal delivery of IL-4 expression plasmid ameliorates disease in a mouse model of psoriasis." (PMID 23472158, 2013). "Interestingly, the replacement of IL-4 and IL-13 by IL-17 from this cocktail is able to mimic in vitro a “psoriasis-like” status on keratinocytes." (PMID 23193414, 2012). "Our results provide a novelmechanism in keratinocytes by which IL-4 improves psoriasis." (PMID 21611195, 2011). "In a clinicaltrial IL-4 was previously shown to effectively clear psoriasis." (PMID 21611195, 2011). "Psoriasis is associated with over-expression of T-helper cell type 1 (Th1) cytokines, IFN-γ and TNF-α in the involved skin and relative underexpression of T-helper cell type 2 (Th2) cytokines, interleukin IL-4 and IL-10." (PMID 21152006, 2010). "As proposed previously, an effective therapeutic strategy in psoriasis may not only involve suppression of Th1 and Th17 responses but also aim to restore immune balance by enhancing Th2-mediated pathways, particularly through cytokines such as IL-4 and IL-13." (PMID 40650209, 2025). "Therefore, the authors believe that blocking the Th2 response by targeting the IL-4 signaling pathway may lead to Th1/Th17 phenotypic transition, resulting in an inflammatory cytokine cascade, ultimately showing psoriasis skin lesions." (PMID 37408052, 2023). "According to a cross-sectional study, psoriasis patients had increased proinflammatory macrophage type 1 (IL-1, IL-6, TNF-α), Th1 (IL-2, IL-12, IFN-γ), Th17 (IL-6, IL-17) but also anti-inflammatory Th2/T regulatory (Treg) (IL-4, IL-10) profiles which may be correlated to the severity of psoriasis." (PMID 31649677, 2019). "AD models can be generated by adding TH2 cytokines such as IL-4 and IL-13, and TNF-α, whereas psoriasis models are induced by treating skin models with cytokine cocktails based on IL-17, IL-22 and TNF-α." (PMID 38251799, 2024). "This interruption in cytokine signaling effectively reduces the inflammatory response mediated by cytokines such as IL-4, IL-13, IL-31, IL-22, and IFN-γ, which are critical in conditions like AD, psoriasis, and alopecia areata (AA)." (PMID 39610670, 2024). "We do not see a statistically meaningful correlation between circulating levels of IL-4, IL-12, IL-22, IL-23, IL-35, IL-36 and TGF-β with the development of psoriasis." (PMID 37883350, 2023). "Sensing of TNFα and IL22 serum levels using the corresponding receptors and linking their downstream signaling in an AND-gate logic enabled the expression of the anti-inflammatory cytokines IL4 and IL10 to treat psoriasis or prevent its development." (PMID 36225597, 2022). "Following culture with GM-CSF, IL-4 and TGF-β, CD14+ monocytes derived from both healthy controls and patients with psoriasis acquired a DC-like phenotype, with CD14 expression decreasing to negligible levels in both groups." (PMID 21933242, 2012). "The proportion of CD8+CCR4+ T cells is increased in the peripheral blood of patients with psoriasis and palmoplantar pustulosis, and CD8+CCR4+ T cells effectively produce IL-4, IFN-γ, IL-2, and TNF-α." (PMID 21483764, 2011). "Gene interaction analyses highlighted IFNG, IL4, IL10, MMP9 and TIMP1 in IBD; IL10, IL13 and PTGS2 in psoriasis; IL8, IL10 and PTGS2 in RA." (PMID 20444268, 2010). "Here, we investigated the expression of psoriasis-related cytokines (TNF-α, IL-6, IL-22, IL-23, IL-17A, IL-17E, IL-17F, IL-4 and IL-10) in the inflamed skin after mannan exposure at the peak (day 4) and the end (day 7) of psoriasis with/without inhibitor(s) treatment." (PMID 38444844, 2024).
psoriasis (continued). "We found no apparent association between levels of IL-4, IL-12, IL-22, IL-23, IL-35, IL-36 and TGF-β in circulation and the risk of psoriasis." (PMID 37883350, 2023). "Although the cytokines such as IL-4, IL-10, and IL-13 play a relevant role in the pathophysiology of psoriasis, the corresponding inhibitors in clinical trials have not yet achieved the expected efficacy." (PMID 36618400, 2022). "Moreover, sensors can cure psoriasis through sensing TNF-a and IL-22 as biomarkers of psoriasis with the following expression of the therapeutic cytokines IL-4 and IL-10." (PMID 34829757, 2021). "Interestingly, adaptive T-cell-derived cytokines IL17A, IL17F, IL17C, IL26, IFNG, IL4, and IL10 show comparable levels in skin biopsies from paradoxical and classical psoriasis." (PMID 29295985, 2018). "Serum levels of IL-1β, IL-4, IL-10, IL-12, IL-17, IL-21, IL-23, visfatin and omentin were not significantly different between psoriasis patients and controls (all P > 0.05)." (PMID 29416693, 2018). "It is noteworthy that IL-4 therapy improves psoriasis in humans by suppressing IL-23/Th17 responses without blocking IL-12-dependent Th1 responses." (PMID 26229971, 2015). "While Th2 cytokines such as IL-4, IL-13, IL-33, and TSLP dominated the inflammatory landscape in AD and bullous pemphigoid, Th1 and Th17 immune responses, primarily mediated by IFN-γ and IL-17, characterized psoriasis, lichen planus, and specific forms of GvHD." (PMID 41479908, 2025). "In psoriasis patients, we expected to see primarily IFNγ signatures rather than IL‐4 + IL‐13." (PMID 40926620, 2025). "Furthermore, IL‐4 upregulates the expression of the transcription factor GATA3 in epidermal cells and keratinocytes, promoting Th2 immune responses while counteracting the proinflammatory Th1 and Th17 responses commonly observed in psoriasis." (PMID 41211170, 2025). "Interestingly, Th2 cytokines such as IL-4 and IL-13, expressed by MCs, and suggested as signalling bridges between immune sense and nerve fibres, were not modulated in MCs in psoriasis." (PMID 37681909, 2023). "Thirty psoriasis patients were subjectedto a ketogenic nutritional regimen and monitored by evaluating (i)the clinical symptoms, (ii) the blood biochemical parameters, includingIL-2, IL-1β, TNF-α, IFN-γ, and IL-4, and (iii) themetabolomic profile, as derived from 1H NMR analysis." (PMID 33164516, 2021). "Here we show that in keratinocytes GATA3 is strongly induced by IL-4.Psoriasis is currently viewed as a predominantly Th1/Th17 disease, where the Th1cytokines (IFN-γ) and Th17 cytokines (IL-17, IL-22) together with IL-23 suppressthe production of IL-4 in T lymphocytes." (PMID 21611195, 2011). "TOX and IL-4 expression was significantly higher in the epidermis of CTCL plaques, whereas it was nearly absent in CS or psoriasis." (PMID 34220814, 2021). "In psoriasis, CCL4, GZMK and KLRF1 show significantly higher, while ADM, ANXA3, IL4, MMP9 and OLR1 show significantly lower expression levels in patients with arthritis negative psoriasis compared to patients with symptoms of arthritis." (PMID 20444268, 2010).